VPS52 (VPS52 subunit of GARP complex)
Description:
Acts as a component of the GARP complex that is involved in retrograde transport from early and late endosomes to the trans-Golgi network (TGN). The GARP complex is required for the maintenance of the cycling of mannose 6-phosphate receptors between the TGN and endosomes, this cycling is necessary for proper lysosomal sorting of acid hydrolases such as CTSD. Acts as a component of the EARP complex that is involved in endocytic recycling. The EARP complex associates with Rab4-positive endosomes and promotes recycling of internalized transferrin receptor (TFRC) to the plasma membrane.
Synonyms: SACM2L; ARE1; SAC2; dJ1033B10.5
Tractability: Antibody: UniProt places it where antibodies can reach, with high confidence. PROTAC: ubiquitination databases record sites on it; its protein half-life has been measured.
Gene: Protein-coding gene on chromosome 6 (33,250,272 to 33,272,047, reverse strand). Ensembl gene ENSG00000223501.
Subcellular location: Golgi apparatus, trans-Golgi network membrane; Endosome membrane; Recycling endosome
Pathways (Reactome):
Vesicle-mediated transport: Retrograde transport at the Trans-Golgi-Network
Gene Ontology:
Molecular function: protein binding; syntaxin binding
Biological process: endocytic recycling; lysosomal transport; Golgi to vacuole transport; retrograde transport, endosome to Golgi; protein targeting; vesicle-mediated cholesterol transport
Cellular component: EARP complex; endosome membrane; GARP complex; Golgi apparatus; membrane; perinuclear region of cytoplasm; recycling endosome; trans-Golgi network membrane; cytosol; postsynapse; presynapse
Genetic constraint (gnomAD): Loss-of-function variants: 55 observed, 101.05 expected, observed/expected ratio (o/e) 0.54, 90% interval 0.44 to 0.68. The upper end of that interval is the gene's LOEUF score, 0.68, which puts it in group 2 of 6, group 1 being the genes least tolerant of losing a copy. Missense variants: 741 observed, 953.91 expected, observed/expected ratio (o/e) 0.78, 90% interval 0.73 to 0.82. Synonymous variants: 348 observed, 357.63 expected, observed/expected ratio (o/e) 0.97, 90% interval 0.89 to 1.06.
Homologues: Orthologues: chimpanzee VPS52 (100% identical), rabbit VPS52 (99% identical), guinea pig VPS52 (99% identical), pig VPS52 (98% identical), rat Vps52 (98% identical), dog VPS52 (98% identical), mouse Vps52 (98% identical), macaque VPS52 (96% identical), zebrafish vps52 (72% identical), tropical clawed frog vps52 (72% identical), Drosophila melanogaster Vps52 (47% identical), Caenorhabditis elegans vps-52 (34% identical).
Diseases named in the same sentence as VPS52 in open-access papers:
VPS52 is named in the same sentence as 13 diseases in open-access papers, as found by Europe PMC text mining. Sharing a sentence is not in itself a finding about the gene and the disease. The quoted sentences say what the papers report.
amyotrophic lateral sclerosis (1 paper, 2016). Amyotrophic lateral sclerosis (ALS) is a neurodegenerative disease characterized by progressive muscular paralysis reflecting degeneration of motor neurons in the primary motor cortex, corticospinal tracts, brainstem and spinal cord. "Mutations in VPS54 and VPS52 lead to neurological disorders in mice that have been studied as models of the human diseases amyotrophic lateral sclerosis (ALS) and the seizure disorder high-pressure nervous syndrome, respectively." (PMID 27191843, 2016).
cervical cancer (1 paper, 2023). A primary or metastatic malignant neoplasm involving the cervix. "The enriched genes included CD4 in cervical cancer, VPS52, NUP62, CRYGD, IL34, GATA3 in prostate cancer and F11, TXNIP, KIT, ASGR2, SERPINF1 in liver cancer, which also provide insight into the molecular mechanisms underlying cancer progression and the potential impact on patient survival." (PMID 37393582, 2023).
gastric cancer (1 paper, 2023). A primary or metastatic malignant neoplasm involving the stomach. "Loss of heterozygosity (9/17 samples) and a stop-gain mutation of VPS52 were discovered in the tissues of gastric cancer." (PMID 37047041, 2023). "In gastric cancer cell lines, there is a lower basal expression of VPS52, in contrast to normal gastric epithelial cell lines." (PMID 37047041, 2023).
Parkinson disease (1 paper, 2022). A progressive degenerative disorder of the central nervous system characterized by loss of dopamine producing neurons in the substantia nigra and the presence of Lewy bodies in the substantia nigra and locus coeruleus. "Mutations in VPS52 can exacerbate Parkinson disease-associated toxicity." (PMID 36578782, 2022). "Protein kinase LRRK2 involved in Parkinson disease is shown to interact with VPS52 to assist in membrane fusion at the TGN thereby acting as a scaffold between the GARP complex and SNAREs." (PMID 36578782, 2022).
schizophrenia (1 paper, 2019). A major psychotic disorder characterized by abnormalities in the perception or expression of reality. "Moreover, four DMRs were located at genes (VPS52, TCIRG1, and TRIM39) that were found to be differentially methylated in the largest schizophrenia (SCZ) whole-blood epigenome-wide association study (EWAS) to date." (PMID 31639064, 2019).
tumor (2 papers, 2023). "Overexpression of VPS52 in vivo has decreased tumor weight and volume." (PMID 37047041, 2023). "Fortunately, VP41 was downregulated and VPS52 was upregulated by BF-TK/GCV treatment, implying inhibition of tumor viability and growth." (PMID 37511481, 2023).
neurological disorders (1 paper, 2016). "It will also be interesting to determine whether neurological diseases associated with VPS52 and VPS53 are caused by dysfunction of GARP or EARP or both." (PMID 27191843, 2016).
VPS52 also shares sentences with these, for which no sentence is quoted: breast carcinoma (1 paper); cancer (1); liver cancer (1); prostate carcinoma (1); seizure disorder (1); viral infection (1).